C5orf52 (chromosome 5 open reading frame 52)
Tractability: No criterion of Open Targets' tractability assessment is met for any kind of drug.
Gene: Protein-coding gene on chromosome 5 (157,671,533 to 157,680,158, forward strand). Ensembl gene ENSG00000187658.
Genetic constraint (gnomAD): Loss-of-function variants: 8 observed, 12.56 expected, observed/expected ratio (o/e) 0.64, 90% interval 0.37 to 1.15. The upper end of that interval is the gene's LOEUF score, 1.15, which puts it in group 5 of 6, group 1 being the genes least tolerant of losing a copy. Missense variants: 193 observed, 209.48 expected, observed/expected ratio (o/e) 0.92, 90% interval 0.82 to 1.04. Synonymous variants: 78 observed, 90 expected, observed/expected ratio (o/e) 0.87, 90% interval 0.72 to 1.05.
Homologues: Orthologues: chimpanzee C5H5orf52 (99% identical), pig C5orf52 (64% identical), dog C26H5orf52 (60% identical), rat C14h5orf52 (52% identical), mouse 4921536K21Rik (52% identical).